TCEAL3 (transcription elongation factor A like 3)
Description:
May be involved in transcriptional regulation.
Synonyms: MGC15737; WEX8
Tractability: PROTAC: its protein half-life has been measured.
Gene: Protein-coding gene on chromosome X (103,607,451 to 103,629,690, forward strand). Ensembl gene ENSG00000196507.
Subcellular location: Nucleus
Subcellular location (Human Protein Atlas): Nucleoplasm
Gene Ontology:
Cellular component: nucleus
Homologues: Orthologues: macaque TCEAL6 (94% identical), dog TCEAL3 (82% identical), dog TCEAL6 (80% identical), mouse Tceal6 (74% identical), mouse Tceal3 (74% identical), rat Tceal3 (73% identical), rat Tceal6 (73% identical), mouse Tceal5 (69% identical), rat Tceal5 (68% identical). Paralogues in human: TCEAL6 (96% identical), TCEAL5 (91% identical), TCEAL4 (51% identical), TCEAL2 (48% identical), TCEAL8 (20% identical), TCEAL1 (18% identical), TCEAL9 (16% identical), TCEAL7 (16% identical).
Diseases named in the same sentence as TCEAL3 in open-access papers:
TCEAL3 is named in the same sentence as 1 disease in open-access papers, as found by Europe PMC text mining. Sharing a sentence is not in itself a finding about the gene and the disease. The quoted sentences say what the papers report.
gastric cancer (1 paper, 2013). A primary or metastatic malignant neoplasm involving the stomach. "A real-time quantitative PCR was performed on normal gastricepithelial cell line GES1 and gastric cancer cell lines including AGS, MKN45, MGC803, SGC7901 and HGC27 to determine the mRNA levels of TCEAL1, TCEAL3, TCEAL4, TCEAL5, TCEAL7 and TCEAL8." (PMID 23372750, 2013). "The TCEAL7 expression level was significantly lower in the gastric cancer cell lines comparing with the levels of TCEAL1, TCEAL3, TCEAL4, TCEAL5 and TCEAL8." (PMID 23372750, 2013).